FOXP3 (forkhead box P3)
Diseases named in the same sentence as FOXP3 in open-access papers (continued):
Sharing a sentence is not in itself a finding about the gene and the disease.
tumor (continued). "For further confirmation, we have co-cultured FOXP3-ablated CD8+ T cells in in vitro tumor milieu and checked the status of CTLA4-positivity." (PMID 28487507, 2017). "The MFI of GARP expression by Foxp3+ Tregs [2216 (1628, 2863)] was almost twofold greater than that by Foxp3− Tconvs [752.0 (483.0, 1040), P < 0.0001] from tumor tissues." (PMID 28261204, 2017). "Increased levels of FOXP3+Tregs in peripheral blood and tumor microenvironment have been reported in diverse cancer types, including the breast one." (PMID 28713192, 2017). "We chose to re-derive immune signature marker sets directly from TCGA tumor data using a handful of sentinel markers (FOXP3, CD8A, CD19, etc.)for immune cells and utilizing mutual rank distance metrics to expand the local gene expression neighborhoods." (PMID 28749946, 2017). "In this, in vitro-generated tumor microenvironment, we observed that perturbation of TGFβ-signalling significantly inhibited FOXP3+CD8+ Treg cell generation." (PMID 28487507, 2017). "In contrast, over-expression of FOXP3 in Hep3B and 97H cells resulted in significantly reduced tumor proliferation (*P < 0.05, **P < 0.01) and cell migration (P = 0.003 and P = 0.014 for Hep3B and 97H, respectively) compared to control cells." (PMID 28903735, 2017). "The number of infiltrated Foxp3+ Tregs decreased in the tumor center, but increased in the peri-tumor tissue." (PMID 29312633, 2017). "Fifthly, the relationship between tumor-infiltrating FoxP3+ Tregs and clinicopathological features was also evaluated in the present meta-analysis." (PMID 29209232, 2017). "We measured the number of tumor-specific CD8+ T lymphocytes and Foxp3+CD4+CD25+ Treg cells in tumor-bearing db/db mice." (PMID 28496193, 2017). "In a transgenic adenocarcinoma mouse prostate (TRAMP) model of prostate cancer, CD4+CD25+FoxP3+ Tregs were found to be dispensable for induction of tumor-specific tolerance." (PMID 28292326, 2017). "We previously demonstrated that CD4+ Foxp3+ Tregs elicit tumor-promoting functions during CAC in mice." (PMID 28938014, 2017). "In contrast to primary NPC, more than half of the patients with recurrent NPC had increased percentages of Galectin-9+ tumour cells and of Foxp3+ lymphocytes." (PMID 28871094, 2017). "Here, we used anti-CD25-Ce6-targeted PDT, in which the anti-CD25-Ce6 complex selectively binds to tumor-infiltrated CD4+Foxp3+ Tregs and kill them locally in the tumor microenvironment by irradiation." (PMID 28537894, 2017). "On the other hand, recent evidence demonstrated that the number of CD4+CD25+FOXP3+ regulatory T cells (Treg), which mediate immunosuppression and play an important role in tumour immune evasion, also increases with age." (PMID 28253320, 2017). "Evaluation of immune cell infiltrates (so-called “immunoscoring”) has shown that the increased expression of Foxp3 in lymphocytes or in tumor cells and an increased Foxp3/CD8+ ratio are related to tumor progression." (PMID 28470464, 2017). "When we compared the expression of all immunologic markers in the tumour microenvironment between primary and recurrent NPC, we found significant differences in the mean percentages of Galectin-9+ tumour cells, Foxp3+ lymphocytes and CD8+ lymphocytes." (PMID 28871094, 2017). "To our knowledge, we for the first time reporting that GATA3 plays a bi-functional role in the transcriptional regulation of FOXP3 in tumor-induced CD8+ Treg cells." (PMID 28487507, 2017). "The cumulative results show the intricate transcriptional regulation of FOXP3 is controlled by three transcription factors, SMAD3, GATA3, and RUNX3, involving CNSs and promoter regions of FOXP3 in tumor-induced CD8+ Treg cells." (PMID 28487507, 2017). "Using the ER-specific antagonist ICI 182,780 (ICI), we further show that ERα modulates FOXP3 expression and suppressive function of Treg cells isolated from CxCa tumour tissues." (PMID 29229929, 2017).
tumor (continued). "We found that knock-down of FOXP3 in Hep3B and 97H cells led to obviously enhanced tumor proliferation (*P < 0.05, **P < 0.01) and cell migration (P = 0.009 and P = 0.002 for Hep3B and 97H, respectively) compared to control cells in vitro." (PMID 28903735, 2017). "The percentages of Galectin-9+ tumour cells and Foxp3+ lymphocytes increased significantly (p < 0.001 and p < 0.001, respectively) in recurrent NPC." (PMID 28871094, 2017). "As a result, the plot showed that all the individual studies had no important impact on the results for 1, 3, 5 or 10-year OS, which correlating with FoxP3+ Tregs both in stroma and intraepithelium within tumor." (PMID 29088871, 2017). "The data reveal the importance of RORγt in the tumour-associated induction of a distinct Treg phenotype, and suggest a difference in the development of Foxp3+ Treg cells in the setting of tumour compared with other microenvironments." (PMID 28290453, 2017). "The combination of OX40L-FP and MVA-Twist-TRICOM significantly expanded the total number of CD4+Foxp3- T-cells at the metastatic tumor site (lung) by at least 2.1-fold compared to the individual treatments 28 days after tumor transplant." (PMID 29207606, 2017). "Our data demonstrate that tumour-induced Th17 cells progressively transdifferentiate into IL-17A+Foxp3+ and ex-Th17 IL-17AnegFoxp3+ T cells during tumour development." (PMID 28290453, 2017). "Nonetheless, these data provide compelling evidence that intracellular complexes of E2:ERα play a vital role in the functional regulation of human FOXP3+ Treg cells that infiltrate human CxCa tumours." (PMID 29229929, 2017). "Average of two reviewers’ value was the final result and expression percentage>median was defined as high expression of FOXP3 in tumor cells." (PMID 28029650, 2017). "In this study, we found that high tumor FOXP3 expression was significantly correlated with worse overall survival and recurrence-free survival of the patients, and showed independent prognostic value in NSCLC." (PMID 28716029, 2017). "Tumor infiltrating lymphocytes as well as its FOXP3+, CD68+, IL-17+ phenotypes in both intratumoral and stromal sites and expression of FOXP3 in cancer cells were assessed." (PMID 28029650, 2017). "Accordingly, we have presented evidence that E2:ERα interactions with FOXP3 locus exert potent effects on gene expression and can modulate the suppressive function of primary human tumor infiltrating Treg cells in patients with CxCa." (PMID 29229929, 2017). "We also investigated the immunological impact of chemotherapy on CD8+ and Foxp3+ T cells in the ESCC tumor microenvironment." (PMID 28404915, 2017). "The prevalence of FOXP3+CD4+CD56+ T cells in tumor-infiltrating lymphocytes (TILs) was moreover found to be inversely correlated with patient survival." (PMID 28791027, 2017). "In the context of cancer, a crucial finding has been that IL-21 reduces the frequency of human FOXP3+ Treg cells by greater than 10-fold during tumour antigen stimulations." (PMID 28239749, 2017). "Our findings suggest that FOXP3 suppresses tumor progression in HCC via TGF-β/Smad2/3 signaling pathway, highlighting the role of FOXP3 as a prognostic factor and novel target for an optimal therapy against this fatal malignancy." (PMID 28903735, 2017). "Herein, we conducted a meta-analysis including 17 published studies with 3811 patients identified from PubMed and EBSCO to assess the prognostic impact of tumor-infiltrating FoxP3+ Tregs in human CRC." (PMID 29088871, 2017). "Given that the development of Tregs is under the influence of various inductive signals, most importantly TGF-β1, we found a significantly increased population of CD4+ Foxp3+ Tregs in the tumor of 2cKO mice." (PMID 28592285, 2017). "Studies have shown that expression of B7-H4 within the tumor microenvironment can increase the function and quantity of FOXP3+ regulatory T cells (Treg cells) and facilitate the immune tolerance also infiltration capacity of Treg cells." (PMID 28978159, 2017).
tumor (continued). "FOXP3 has been discovered to be expressed in tumor cells and participate in the regulation of tumor behavior." (PMID 28903735, 2017). "Previous studies have indicated that artificially designed deletions of the N-terminal portion, C-terminal portion, zinc finger domain or leucine zipper domain of FOXP3 resulted in reduced tumor suppressive activities." (PMID 28903735, 2017). "In the present study, elevated A2AR was detected on the surface of CD4+ Foxp3+ Tregs in 2cKO tumor bearing mice, emphasizing the potential role of A2AR signaling in regulating the expansion or functions of Tregs in HNSCC." (PMID 28592285, 2017). "In fact, FoxP3+ cells are more often detected in advanced tumor stages with lymph node involvement, and are likely to be located in the surrounding stroma, which we did not consider in the present study." (PMID 28885584, 2017). "The tumor cells with down-regulation of FOXP3 grew to a significantly heavier weight (P = 0.030 and P = 0.040 for Hep3B and 97H, respectively) compared with controls." (PMID 28903735, 2017). "We can say, cells that can inhibit antitumor immune responses and promote tumor growth are FoxP3+ T cells." (PMID 29450136, 2017). "The presence of >11 FoxP3+ lymphocytes/hpf in the tumor stroma was related to an unfavorable prognosis regarding both DFS and OS (p < 0.0001, log-rank test)." (PMID 28343267, 2017). "Previous meta-analyses reported that increased tumor-infiltrating FoxP3+ Tregs improved OS in human CRC." (PMID 29088871, 2017). "Functional analysis of CD4+ T cells has recognized CD25+FOXP3+CD4+ Tregs cells which have been found to suppress the tumor specific immune response." (PMID 28515351, 2017). "While our results indicate that OX alone is capable of increasing the CD8+/Foxp3+ ratio at local and systemic tumor sites, the co-administration of a PL-conjugated IDO inhibitor, IND-PL, significantly enhanced the response parameter." (PMID 29180759, 2017). "To assess the effects of oncolytic Ads on the CD4+CD25+Foxp3+ Treg cell population, we examined draining lymph nodes (DLNs) from tumor-bearing mice by fluorescence-activated cell sorting (FACS)." (PMID 28002796, 2017). "The mean overall survival time of patients with high FOXP3 expression in tumor tissues was 44.3 ± 6.54 months, while that with low FOXP3 expression level was 78.1 ± 7.35 months (P = 0.007)." (PMID 28716029, 2017). "We also noticed a significant increase in the percentage of CD25+Foxp3+ cells in CD4+ T cells after tumor resection." (PMID 28178645, 2017). "Tumor FOXP3 expression mainly exhibited a mixture of diffuse staining in the cytoplasm, the nucleus or in both of them." (PMID 28716029, 2017). "When Cyclophosphamide was combined with cryoablation in a murine colorectal model, the proliferation of tumor specific T cells was greatly increased as was the ratio of effector CD4+ T cells to regulatory FoxP3+ T cells." (PMID 29037259, 2017). "The promotion of tumor growth and metastasis by FOXP3 was further confirmed in subcutaneous xenograft tumor mouse model and tail-vein-injection metastatic mouse model." (PMID 28716029, 2017). "Normal mammary epithelial cells express higher functional levels of Foxp3 compared to tumor cells and comparable levels of endogenous Runx1 mRNA." (PMID 26735887, 2016). "NSCLC tumors also have elevated expression of the chemokine CCL20, which aids in the recruitment of FOXP3+ Treg cells into the tumor microenvironment." (PMID 27416962, 2016). "FOXP3+ Tregs suppressed the function of effector T cells to destroy maintenance of immune balance which resulted in the escape of tumor immunological surveillance." (PMID 27566250, 2016). "A total of 126 patients with surgically resected stage I NSCLC were included to perform immunohistochemistry of CD8+ tumor infiltrating lymphocytes (TILs), programmed death ligand-1(PD-L1) and forkhead box P3 (Foxp3)+TILs." (PMID 27602763, 2016).
tumor (continued). "Multiple previous studies have shown that tumor-specific CD4+FoxP3 Tregs express multiple inhibitory receptors, including PD-1 and TIM3, which likely reduce the capacity of T cells in the tumor microenvironment for proliferation and cytokine production." (PMID 26943572, 2016). "The reason why higher infiltration of regulatory FOXp3+ cells showed favourable prognosis in this study is complex but has been reported in gastric and other tumour types." (PMID 27020682, 2016). "More studies are needed to further explore how tumor cells regulating the metastasis behavior during this interaction, especially in light of the current anticancer efforts to interfere with Foxp3 expression." (PMID 27457382, 2016). "According to our data, the ratio of FOXP3+ vs CD4+ or CD8+ cells in both the tumor and stromal compartment had a prognostic value." (PMID 27463005, 2016). "TNFR2 expression was also observed for splenic CD4+Foxp3+ Treg cells in naïve and tumor-bearing animals, and human peripheral blood Treg cells, confirming constitutive expression by Treg cells in the periphery of both species." (PMID 27626702, 2016). "The expression of CD103 in lymphoid CD4+Foxp3+ cells was reported to recruit Tregs into tumor sites." (PMID 27036297, 2016). "In the present study, we investigated the tumor cell Foxp3 expression in a large 273 case OSCC cohort and determined the correlation of Foxp3 with clinicopathologic factors, relapse, and prognostic significance of OSCC." (PMID 27457382, 2016). "We found that OSCC patients with high tumor Foxp3 expression had significantly shorter survival time and more lymphnodes involvement than other groups." (PMID 27457382, 2016). "CD200R/Foxp3-mediated microglial activation is similar to immunosuppressive type 2 differentiation of macrophages in tumour microenvironments." (PMID 27731341, 2016). "The CD39+Foxp3+Tregs count added prognostic power to Foxp3+Tregs, providing a potential target for tumor immunotherapy." (PMID 27749555, 2016). "Nrp-1 is highly expressed by Foxp3+ Tregs, which appear to regulate immunological anti-tumor control mechanisms in response to tumor-derived VEGF39." (PMID 27075020, 2016). "Our results are in accordance with the previous ones in that the tumor-infiltrated lymphocytes isolated from the liver tumor models have high levels of FOXP3." (PMID 27716621, 2016). "Our results demonstrated that the Treg (CD4+CD25+FoxP3+) cell population was significantly decreased in the spleen and also in the tumor of the BME-fed mice as compared to control animals, suggesting the immunomodulatory role of BME." (PMID 27120805, 2016). "Additional evidence for the presence of regulatory T-cells in sarcoids was provided by immune-staining which showed that FOXP3 protein is ubiquitously present in the nuclei of sarcoid infiltrating T-cells as well as within the tumour fibroblasts themselves." (PMID 27160146, 2016). "FOXP3+ T cells are reported to be increased in tumor-bearing patients or animals and are considered to suppress antitumor immunity, but the evidence is often contradictory." (PMID 26864030, 2016). "The number of Foxp3+CD25+CD4+ cells is significantly lower within the tumor cell area as compared to the number outside the tumor cell area." (PMID 27999289, 2016). "Intriguingly, our data showed that the majority of tumor-infiltrating FoxP3+ T cells were aTreg cells." (PMID 27177223, 2016). "In order to do that, we treated the mice with Foxp3 blockade peptide (P60) that inhibited Treg function transiently and we boosted the tumor immune response with Gvax (GM-CSF producing B16-F10 irradiated cells) immunization." (PMID 26992239, 2016). "In tumor cells Foxp3 low expression would explain high transcriptional activity of Runx1 on Rspo3 promoter." (PMID 26735887, 2016). "Regulatory T cells (Tregs, CD4+CD25+FoxP3+) also stimulate immune tolerance and facilitate tumor progression." (PMID 26862849, 2016).
tumor (continued). "Accordingly, the subclassification of FOXP3+ T cells is fundamental for revealing the significance of FOXP3+ T cells in tumor immunity, but the arbitrariness and complexity of manual gating have complicated the issue." (PMID 26864030, 2016). "Regulatory T cells (Tregs, CD4+CD25+FoxP3+) stimulate immune tolerance and facilitate tumor progression." (PMID 26862849, 2016). "In NSCLC, increased tumor infiltration with CD8+ T cells is associated with improved survival 25, whereas higher infiltration by FOXP3+ Treg cells is associated with disease recurrence." (PMID 27416962, 2016). "An accumulation of highly suppressive and activated FoxP3+ TI Tregs in the tumor tissue of CRC patients has also been reported to correlate with tumor progression." (PMID 27509527, 2016). "We conclude that Nrp-1 is highly expressed by Tregs that control Foxp3+ Treg migration into the tumor, and this process is highly dependent on tumor-derived IL-10." (PMID 27075020, 2016). "The higher Treg levels in tumour tissues indicated a worse prognosis and the FOXP3+ Tregs/CD4+ T cell ratio was an independent prognostic factor for OS." (PMID 27725696, 2016). "Regulatory T cells (Tregs), particularly the CD4+CD25+Foxp3+ Tregs, down regulate immunity and promote tumor cell growth by directly suppressing CD8+ and CD4+ T cells." (PMID 27389040, 2016). "All tumor-infiltrating immune cells except FOXP3+ lymphocytes presented a heterogeneous density according to tumor location." (PMID 27835889, 2016). "With their immunosuppressive functions, Treg infiltration, and perhaps more importantly, ICOS+ FOXP3+ Treg infiltration, plays critical roles in tumour progression and clinical behaviour by modifying the host’s immune response." (PMID 27725696, 2016). "We explored OS based on TIICs in the stroma by focusing on factors significantly impacting OS in the tumor nest assessment (CD8+/FOXP3+, CD8+/CD204+, and PD-1+)." (PMID 27322149, 2016). "It promotes the generation and effector functions of antigen-specific CD8+ T cells, modulates Foxp3-expressing regulatory T cell responses, and programs effector T cells into a unique T-effector stem cell phenotype in the tumor microenvironment." (PMID 27403033, 2016). "The proportion of CD4+ cells displaying regulatory T cells characteristics, as evaluated by the expression of CD25 and FoxP3, was significantly lower in the tumor lysates from VV-FCU1-treated animals in comparison to that of controls." (PMID 27057460, 2016). "The late accumulation of high numbers of CD25+Foxp3+ Tregs cells (D14) in the DLN of treated mice indicates that Tregs suppressive effects are likely to occur mainly at the initial phase of the anti-tumour response." (PMID 27341421, 2016). "FOXP3-induced miR-146a/b prevents tumor cell proliferation and enhances apoptosis in ER-positive breast cancer cells." (PMID 26418898, 2016). "TNFR2 expression was observed for CD4+Foxp3+ Treg and NKp46+ NK cells in all tissues examined, and was additionally observed for tumor-infiltrating CD4+Foxp3− and CD8+ T cells, and for splenic CD11b+Gr1+ myeloid cells from tumor-bearing animals." (PMID 27626702, 2016). "Tregs maintain homeostasis in immunity; our data suggest that Foxp3+ Tregs obtained from IL-10−/− B16/F10 tumor-bearing mice become unstable after antigen stimulation depriving them of Foxp3+ expression." (PMID 27075020, 2016). "FOXP3+ Tregs, which are mostly ICOS+ FOXP3+ Tregs in HCC tumour tissues, are the main immuno-suppressors in the liver carcinoma microenvironment." (PMID 27725696, 2016). "A recent study found that in colorectal cancer, functionally distinct subsets of tumor-infiltrating Foxp3+ T cells contribute in opposing ways to measuring outcomes." (PMID 27999575, 2016). "Higher levels of Foxp3+ regulatory T (Treg) cells have been reported in numerous cancers, including other EBV-associated tumors, and are thought to limit anti-tumor immunity." (PMID 28033393, 2016).